STK11 (serine/threonine kinase 11)
Diseases named in the same sentence as STK11 in open-access papers (continued):
Sharing a sentence is not in itself a finding about the gene and the disease.
cervical carcinoma (79 papers, 2009 to 2026). A carcinoma arising from either the exocervical squamous epithelium or the endocervical glandular epithelium. "No obvious correlation between these two rare cancers and germline STK11 mutations in PJS has been described; nevertheless, somatic STK11 mutations were detected in approximately 20% of cervical cancers, and half of the harbored mutations were large monoallelic/biallelic deletions." (PMID 36874343, 2023). "The frequent mutation and/or loss of STK11 in C2 tumours observed in our study suggests a similar adeno-SCC transition may be similarly linked to poor prognosis in cervical cancer." (PMID 36207323, 2022). "The mTOR signaling-related gene, STK11, previously reported by our group as a poor prognostic factor for cervical cancer, was altered significantly more frequently in patients with NECC than in those with SCC (16.0% vs. 4.4%, p < 0.05)." (PMID 33802174, 2021). "In our study, STK11 harbored recurrent mutations for two patients along with recurrent chromosomal losses in two metastatic samples, suggesting that STK11 alterations confer the ability of cervical cancers to metastasize." (PMID 33017516, 2020). "STK11 is a known COSMIC tumour suppressor gene, which has been shown to be involved in lung and cervical cancers, and very recently, splice site mutations of the gene were described in relation to cancer." (PMID 28362259, 2017). "STK11/LKB1 is a tumor suppressor gene with lower expression in HeLa cell lines (cervical cancer cells)." (PMID 25522020, 2014). "STK11 mutations and LKB1 loss of function are also found in many other sporadic cancers including lung and cervical cancer." (PMID 22815934, 2012). "STK11 mutations are associated with poor responses to ICI in other cancers, and elucidating the role of STK11 in cervical cancer may improve targeted and immunotherapies." (PMID 41742943, 2026). "Apart from STK11, PIK3CA mutations and YAP1 amplification are prevalent cervical cancer drivers." (PMID 41742943, 2026). "Changes are also noted in the STK11 gene, a known cervical-cancer-silenced HPV tumor suppressor." (PMID 41155343, 2025). "As commercial panels continue to develop, identification of STK11 alterations will become more common leading to the identification of thousands of lung and cervical cancer patients who could potentially benefit from STK11 targeted therapy." (PMID 37035141, 2023).
cervical carcinoma (continued). "In this perspective, STK11 gene, which has been found frequently mutated in HPV-related cervical carcinoma, has been analyzed in HPV-positive and HPV-negative invasive penile cancers to establish its mutational status and the possible correlation of HPV infection with specific genetic alterations." (PMID 23305393, 2013). "Regarding the negative regulation exerted by microRNAs on STK11 expression in human cancers, it has been reported that miR-199a, miR-17 and miR-155 might regulate STK11 expression in cervical cancer; in pancreatic cancer mir-7 represses autophagy via directly targeting LKB1." (PMID 32911741, 2020). "Next, we checked the Cervical Cancer Database (CCDB) and found three genes, haemoglobin alpha 2 (HBA2), mesothelin (MSLN) and STK11, overlapped between 849 genes/loci observed from our current study and 538 genes listed in the CCDB." (PMID 29083376, 2016). "The results showed that STK11 protein expression was not attenuated in the normal endometrium, but it was attenuated in cervical cancer tissue." (PMID 27081568, 2016). "In the HeLa cell, derived from a cervical cancer that had undergone a large deletion in STK11, increases in AMP and ADP do not enhance Thr172 phosphorylation because the basal activity of CaMKKβ is too low to support this unless intracellular Ca2+ is also elevated." (PMID 24467442, 2014).
pancreatic cancer (75 papers, 2009 to 2025). "Among the entire cohort, 2 patients exhibited STK11 mutations, 1 with pancreatic cancer (290+1G>T) and another with NSCLC (721G>C)." (PMID 39886125, 2024). "Serine/threonine kinase 11 (STK11), also known as liver kinase B1 (LKB1), is associated with pancreatic cancer." (PMID 38461159, 2024). "The insights gained from these investigations are crucial for developing novel therapeutic strategies for treating STK11-mutated pancreatic cancers, where innovative and effective treatments are urgently needed." (PMID 38461159, 2024). "Our findings support the adoption of therapeutic strategies, including Roflumilast, for patients with STK11-mutated pancreatic cancer in order to improve treatment efficacy and ultimately prolong survival." (PMID 38461159, 2024). "The lifetime risk of pancreatic cancer is highest for patients with known germline variants in three unique genes: STK11, CDK2NA, and PRSS1." (PMID 37165697, 2023). "Germline STK11 mutant carriers have an increased risk of pancreatic cancer, with 11–36% lifetime risk (by age 70), as well as other malignancies." (PMID 35163129, 2022). "Mutations in the STK11 gene (Peutz-Jeghers) represent a 130-times increased risk of pancreatic cancer relative to the general population." (PMID 35626055, 2022). "A molecular analysis of PDAC revealed that the loss of heterozygosity in tumor suppressor gene STK11/LKB1 plays an important role in both sporadic and familial pancreatic cancer." (PMID 35884779, 2022). "Of the established pancreatic cancer susceptibility genes, the penetrance of pancreatic cancer is highest in patients with pathogenic germline variants in STK11, the gene that causes the Peutz-Jeghers syndrome." (PMID 33555482, 2021). "Screening is recommended for high-risk individuals, including patients with a family history of pancreatic cancer or patients with an STK11, CDKN2A/p16, or a BRCA2 mutation with ≥1 affected first-degree relative." (PMID 28283772, 2017). "LKB-1/STK11 loss sensitizes pancreatic tumor cells to DNA methylation and inhibition of serine biosynthesis, and thus connecting cancer metabolism to DNA methylation and tumorigenesis." (PMID 27999365, 2016). "Mutations in the cell cycle regulator p16/CDKN2A are also associated with familiar pancreatic cancer as are mutations in the serine/threonine kinase STK11/LKB1." (PMID 26840568, 2016). "STK11, a classic tumor suppressor, is mutated in pancreatic cancer and many other types of cancers." (PMID 38461159, 2024). "Here, we identified PDE4, as potential drug targets in STK11-mutated pancreatic cancer." (PMID 38461159, 2024). "Somatic STK11 mutations have been identified in approximately 4% of sporadic pancreatic cancers." (PMID 35163129, 2022). "Similarly, use of everolimus in a patient with Peutz–Jeghers syndrome-induced advanced pancreatic cancer with presumed mTOR hyperactivation through loss of STK11/LKB1 leads to 9 months progression-free survival." (PMID 27200288, 2016). "Mutations in the high penetrance genes such as BRCA2, PALB2, p16/CDKN2A, PRSS1, SPINK1, and STK11 correlate with a very high lifetime risk of developing pancreatic cancer and may cause as many as 10% of pancreatic cancers in the US." (PMID 24883056, 2014). "The pancreatic cancer and NSCLC patients with STK11 mutations were taken off study at 3 and 7 months, respectively, due to grade 3 transaminitis without evidence of progression of disease." (PMID 39886125, 2024).
pancreatic cancer (continued). "In particular, STK11 and PRSS1 are associated with an especially high risk of developing pancreatic cancer, but variants in these genes are very rare." (PMID 38961426, 2024). "Of note, a subset of pancreatic cancers arises in the background of Peutz–Jeghers syndrome (PJS), which is caused by germline alterations in the STK11 gene." (PMID 38201484, 2023). "Over the last decade, the genetics associated with pancreatic cancer has been intricately assessed Some well-known cancer gene germline mutations have been identified in patients with pancreatic cancer, including BRCA1/2, PALB2, STK11, PRSS1, SPINK1 and ATM." (PMID 35813042, 2022). "Inactivation of STK11 plays an important role in carcinogenesis in both sporadic and hereditary pancreatic cancer." (PMID 35163129, 2022). "Genetic syndromes, such as those resulting from inherited mutations in genes like STK11, BRCA1, BRCA2, PALB2, CDKN2A, and DNA repair genes, notably elevate the risk of pancreatic cancer, particularly in individuals with a family history of pancreatic cancer among first-degree relatives." (PMID 39949443, 2025). "Given the higher risk of PDAC in PJS and similar mutations in IPMNs and pancreatic cancer, STK11/LKB1 mutations noted in IPMNs among PJS patients may predispose this patient population to higher rates of progression to PDAC versus the general population." (PMID 35884779, 2022). "Genetic alterations in tumor suppressor genes found in lower frequency (<10%) in pancreatic cancer include STK11/LKB1, MKK4, TGFβ R1 (ALK 5, chromosome 9q), TGFβ R2 (chromosome 3p), ACVR1β (ALK 4, chromosome 12q), ACVR2 (chromosome 2q), FBXW7 (CDC4), EP300, BRCA2, ATM, and AKT2." (PMID 24624093, 2014). "However, several germinal mutations associated with complex familial syndromes have been shown to significantly increase the risk of developing pancreatic cancer (BRCA2, INK4A, STK11/LKB1, PRSS1, hMLH1 and hMSH2)." (PMID 19629168, 2009). "Although chronic pancreatitis is an important risk factor for pancreatic cancer development most of the mutated genes found to contribute to pancreatic cancer susceptibility when defective are classic tumor suppressor genes, such as BRCA2, ATM, PALB2, p16, and STK11." (PMID 28881607, 2017). "We then assessed the effect of serine/threonine kinase 11 (STK11) knockout on pancreatic cancer by wound-healing assay, chick agnosia (CAM) assay, and orthotopic mouse pancreatic cancer model." (PMID 38461159, 2024). "Although more mechanistic studies are required to understand the relationship between STK11 and PDEs in the progression of PDAC, the results reported herein also indicate a potential path for therapeutic intervention with Roflumilast for STK11 mutant pancreatic cancer patients." (PMID 38461159, 2024).
colorectal cancer (49 papers, 2001 to 2025). A primary or metastatic malignant neoplasm that affects the colon or rectum. "It is caused by a GPV in STK11 and is associated with an increased risk of multiple tumours including a 28–34% cumulative risk of developing colorectal cancer by age 64 years." (PMID 37258796, 2023). "Hereditary syndromes are related to the development of colorectal cancer and are caused by germline mutations in genes such as APC, MYH, STK11/LKB1, BMPR1A, SMAD4, and DNA mismatch repair." (PMID 41541272, 2025). "In colorectal cancer, where a murine isograft model was used, STK11 modulated TGFβ signalling, which mediated the exclusion of T-cells and suppressed the differentiation of Th1 cells, resulting in a “cold” tumour immune microenvironment." (PMID 40650126, 2025). "Contrarily, STK11 has been reported to be necessary for the survival of colorectal cancer cells, hepatocyte proliferation, liver regeneration and cell survival of liver tumors with constitutive activation of AKT." (PMID 28109268, 2017). "Although inherited susceptibility is responsible for ∼30% of all colorectal cancers (CRCs), high-penetrance, germline mutations in APC, the mismatch repair (MMR) genes, MUTYH/MYH, SMAD4, ALK3 and STK11/LKB1 account for <5% of cases." (PMID 18362937, 2008). "A minigene assay using expression vectors demonstrated that RNA splicing around exons 2 and 3 of STK11 could be reproduced in the HCT116 human colorectal cancer cell line." (PMID 40830517, 2025). "To test this concept further, we utilised two cell lines with basally high mTORC1 signalling: the NCI-H460 large cell lung cancer cell line which has PI3KCA, CDKN2A, STK11 and KRAS mutations and the HCT116 colorectal cancer cell line, which contains an activating RAS mutation and PIK3CA mutation." (PMID 28415776, 2017). "Creation of isogenic pairs of cancer lines and their controls demonstrated that elimination of STK11/LKB1 expression in 2 primary cancers, human NSCLC and mouse colorectal cancer (CRC), conferred cachexia phenotypes when transplanted into immunocompromised and immunocompetent hosts, respectively." (PMID 37092555, 2023). "Silencing of STK11/LKB1 in human NSCLC and murine colorectal carcinoma lines conferred a cachexia phenotype after cell transplantation into immunodeficient (human NSCLC) and immunocompetent (murine colorectal carcinoma) models." (PMID 37092555, 2023). "In particular, recent published works point out at other genes implied in colorectal cancer pathogenesis (APC, MUTYH, STK11 and BRCA1/2) as explanations of familial colorectal cancer syndromes in patients who do not present mutations in standard MMR protein gene system." (PMID 26485756, 2015). "A study by Lee and colleagues showed that STK11, PRKAA1, and TSC1 polymorphisms were associated with disease-free survival after diagnosis with colorectal cancer; they did not see an association with TSC2." (PMID 25541970, 2014).
hepatocellular carcinoma (47 papers, 2012 to 2025). A malignant tumor that arises from hepatocytes. "In most PJS patients, one allele of STK11 is mutated, causing multiple gastric adenomatous polyps or hepatocellular carcinoma." (PMID 25259881, 2014). "LKB1/STK11 is frequently mutated or undergoes allelic loss in hepatocellular carcinoma." (PMID 36361574, 2022). "Human STK11 gene is located on chromosome 19p13.3; loss-of-function mutations in its coding sequence have been found in lung, breast, cervical, pancreatic and biliary carcinomas, and also in testicular cancer, malignant melanoma, hepatocellular carcinoma, and HNC." (PMID 32911741, 2020). "Lastly, resting mast cells demonstrated a strong positive correlation with PEBP1/STK11 co-expression of in multiple cancers, including hepatocellular carcinoma (LIHC), KICH, KIRC, BRCA, PRAD, LUAD, MESO, THCA, and SARC." (PMID 40806276, 2025). "CCL26, for example, has been shown to be highly expressed in recurrent hepatocellular carcinoma (HCC), while CXCL2 is highly expressed in STK11-mutated NSCLC, which has a poorer response rate to ICIs." (PMID 35145511, 2021).